IL6 (interleukin 6)
Diseases named in the same sentence as IL6 in open-access papers (continued):
Sharing a sentence is not in itself a finding about the gene and the disease.
pneumonia (continued). "The level of IL-6 in patients with pneumonia was significantly lower than that in non-pneumonia patients (87 vs. 162 pg mL−1, P = 0.043) whereas the level of IL-8 was higher (131 vs. 97 pg mL−1, P = 0.026)." (PMID 35280859, 2022). "Pneumonia is characterized by the production of inflammation-related cytokines and chemokines throughout the body, especially in the lungs, including TNF- α, IFN- γ, IL-6 and IL-1β which are controlled by TLR4/NF-κB signaling pathway." (PMID 36530439, 2022). "Therefore, such insufficient levels of IL-6, IFN-γ, ICL, CD16, and CD20 can be considered as predictive criteria of secondary pneumonia in pediatric patients with chickenpox." (PMID 34795992, 2021). "The results showed that serum 25-OH-VD level was negatively correlated with the severity of NIP, whereas Spearman’s correlation analysis showed a significant positive correlation between the severity of NIP and the levels of pneumonia markers procalcitonin (PCT) and interleukin-6 (IL-6)." (PMID 34643152, 2021). "They saw that the macrophages of patients with an exacerbation of COPD without pneumonia had an increase in the amount of arginase mRNA and in the induction of IL-6." (PMID 34418988, 2021). "In addition, significant increase was observed in the TNF-α, IL-6, IL-1β, and MPO in the BALF and lung tissue samples collected from the KP-infected pneumonia mice, which were reversed by anemoside B4." (PMID 32625244, 2020). "IL-6 levels are also increased in the plasma and BALF of patients with pneumonia." (PMID 33114582, 2020). "Irrespective of SARS-CoV-2 or pneumonia in TCGA-LUAD, the altered immunoreaction was the primary cause (lung adenocarcinoma; SARS-CoV-2; ACE2; miR-125b-5p; IL6)." (PMID 32512929, 2020). "Furthermore, H1N1 infection caused significant elevation of mRNA levels by up to 3-6-fold for IL-1β, IL-6, and TNF-α, reinforcing the successful establishment of virus-induced pneumonia." (PMID 32901688, 2020). "The Xue Bi Jing Injection relieved or reduced severe pneumonia by triggering the inflammation pathway through downregulation of TNF-α, IL-6, and IL-8 on the 3rd, 7th, and 14th day after treatment, although it did not significantly influence the release of leptin." (PMID 33746739, 2020). "The optimum critical point of IL-6 in the group was 24.3 pg/ml, which was the upper limit of no severe pneumonia." (PMID 32256705, 2020). "Host factors CRP, IL-1β, hs-CRP, IL-8, and IL-6 levels in severe pneumonia patients were higher than in non-severe patients." (PMID 33065551, 2020). "Among 89 elderly patients with severe pneumonia, the SFI treatment group had significantly decreased levels of TNF-α, IL-6, and IL-8 7 days after administration, indicating that SFI effectively reduced inflammatory mediators, thus, playing an active therapeutic effect." (PMID 32848729, 2020). "Serum IL-6, sCD40L, IL-5 and IL-2 further rose in time point B in patients who developed severe pneumonia, while no such change was seen in patients with DHF." (PMID 33199778, 2020). "Our present results illustrated that co-administration of MSC and LZD significantly decreased the plasma concentrations of systemic cytokines such as CRP, IL-8, IL-6, and TNF-α in MRSA-induced pneumonia compared with LZD treatment alone, which were in line with previous report." (PMID 31484796, 2019). "The difference in IL-6 values between the control and experimental groups was significant, but this difference did not reflect the severity of pneumonia." (PMID 31387541, 2019). "The levels of IL-6, TNF-α, and C-reactive protein were positively correlated with the serum levels of YKL-40, but the IL-10 levels were negatively correlated with YKL-40 levels in all 3 pneumonia subgroups." (PMID 30514252, 2018).
pneumonia (continued). "The significant associations between sequencing-detected abundance of pathogens and host biomarkers of injury and inflammation (RAGE, IL-6, TNFR1) provided further validation of the biological and clinical relevance of sequencing profiles for pneumonia diagnosis." (PMID 30042738, 2018). "In conditions of severe pneumonia in patients serum levels of TNF and IL-6 reach ng quantities." (PMID 28642550, 2017). "Nevertheless, given the results of the meta-analyses it is interesting to consider IL6 and IL10 genotype-dependent expression data in pneumonia or conditions which may precede or follow pneumonia." (PMID 27725770, 2016). "The ratio between the median of IL-6 and IL-10 serum levels in patients with severe and non-severe pneumonia was respectively 22 and 5 at admission, but 9 and 5 on D3, and 3 and 2 on D8 of antibiotics therapy." (PMID 27905908, 2016). "Another study in patients with non-responding pneumonia demonstrated a reduction in inflammatory biomarkers such as IL-6 and IL-8 in bronchoalveolar lavage in patients receiving treatment with corticosteroids plus a macrolide." (PMID 27716262, 2016). "The results showed that urinary values of intestine-FABP, adipocyte-FABP, heart-FABP, and IL-6 were significantly higher and P/F ratio was significantly lower in pneumonia with septic shock than in those without septic shock on day 1 after RICU admission." (PMID 27175705, 2016). "Lung inflammation was not altered in Nod2-/- mice during S. pneumoniae pneumonia, except for elevated levels of IL-6 and MIP-2 in whole lung homogenates." (PMID 26673231, 2015). "Intraperitoneal IL-6 was not affected by extraabdominal infections like pneumonia or urinary tract infection and therefore seems to be more specific than systemic inflammatory parameters." (PMID 26444274, 2015). "Our finding that pro-inflammatory gene expression is stronger in BALB/c mice is in line with several previous studies that compared C67Bl/6 and BALB/c mice: After infection with mcyoplasma pneumonia, the BAL levels of CXCL1, MIP-1α, MCP-1, IL-1b and IL-6 were higher in BALB/c mice." (PMID 22848503, 2012). "At the 'diagnosis of pneumonia', TNF-α, IL-1β, IL-6, IL-8, IL-10 and E-selectin were significantly increased in those patients who had subsequent septic shock, compared to patients with pneumonia without subsequent septic shock." (PMID 16280065, 2005). "For example, the concentrations of cytokines such as interleukin-6 (IL-6), interleukin-8 (IL-8), interleukin-15 (IL-15), and monocyte chemoattractant protein-1 (MCP-1) are markedly elevated, mirroring the cytokine storm observed in severe SARS-CoV-2-induced pneumonia." (PMID 41573583, 2025). "Therefore, future studies should consider increasing sample size, standardizing efficacy evaluation criteria, and further exploring the stratified role of IL-6 and TNF-α levels in severe pneumonia patients to enhance the reliability and applicability of the results." (PMID 40342990, 2025). "In this study, the results showed that IL-1β, IL-6 and TNF-a in control group were lower than those of the model control group, and there were extremely significant statistical differences (p < 0.001), indicating that LPS-induced zebrafish pneumonia models elevated inflammatory factors." (PMID 40271073, 2025). "The cytokines IL-1β, IL-6, and TNF-α, which are key indicators of inflammation, were found to be elevated in the model control group compared to the control group, with extremely significant statistical differences, confirming the inflammatory nature of the LPS-induced pneumonia model." (PMID 40271073, 2025). "Furthermore, IL-6, but not IFN-α, was associated with the development of pneumonia and respiratory failure, which differed from the features of infections with precedent variants before Omicron emerged." (PMID 38694512, 2024).
pneumonia (continued). "However, in an observational study comparing acute respiratory distress syndrome, severe pneumonia, and controls, IL-6 was not significantly different between the groups." (PMID 37733154, 2023). "Notably, pneumonia patients who develop acute kidney injury were older, had more comorbidities, and higher levels of inflammatory cytokines in the blood (IL-6, TNF, D-dimer) even in those without severe disease." (PMID 36870980, 2023). "Second, the study only investigated the associations of blood cell counts and related indicators with pneumonia in cerebral hemorrhage patients, but did not investigate other inflammatory indicators including C-reactive protein, interleukin-6 and other inflammatory factors." (PMID 37904408, 2023). "Interestingly, transplantation of MSC at stage IIa studies found no significant changes in IL-6, although the indicators of pneumonia on CT improved, which coincides with our results." (PMID 36901868, 2023). "In addition to the biomarkers that were associated with the development of hypoxemia (IFN-α, IL-6, CXCL10, LDH, and CRP), VEGF, NLR, and adjusted NT levels were significantly higher in patients with pneumonia than in those without pneumonia." (PMID 37731495, 2023). "IL-6, soluble P-selectin, P-selectin glycoprotein ligand-1, tissue plasminogen activator, plasminogen activator inhibitor, tissue factor, and D-dimer increased in patients with severe pneumonia than those with mild-to-moderate pneumonia and without pneumonia." (PMID 36888618, 2023). "Measurement of inflammatory cytokine levels using ELISA showed that IL-1β, IL-6, TNF-α, IL-2, IL-8, IL-12, and IFN-γ levels were significantly enhanced, while IL-10 levels were significantly reduced in the lung homogenates of Spn-induced pneumonia mice, compared with the normal mice." (PMID 32460745, 2020). "Furthermore, in RAW264.7 cells, SAHA significantly reduced the expression of TNF‐α and IL‐6 in macrophages after LPS stimulation;34 TSA also reduced the IL‐1β level in the serum of a mice model of post‐influenza pneumonia but, interestingly, the acetylation level of histone H3 was not affected." (PMID 32061096, 2020). "Thus, IL-6 produced in the upper respiratory tract seems to be mainly responsible for the induction of systemic symptoms in infected humans, while IL-6 is not directly involved in progression to pneumonia development." (PMID 33062077, 2020). "Serum IL-10 (p = 0.0001), IL-6 (p = 0.002), MIP-3α (p = 0.02) and CD40-L levels (p = 0.002) significantly increased from time point A to B (5–9 day of illness to 10–21 day of illness) in deceased individuals and in those who developed severe pneumonia, when compared to those who had mild illness." (PMID 33199778, 2020). "Interestingly, aSAH patients contracting pneumonia or other infections had significantly higher serum IL-6 levels as compared to those of non-infectious aSAH patients." (PMID 29194369, 2017). "At diagnosis, IL-10 levels were lower (3.68 vesus 1.99, P = 0.074), and IL-6 levels were higher (44.07 versus 19.98, P = 0.155) in children with severe pneumonia than in children with non-severe pneumonia; however, no statistical difference was observed between the two groups." (PMID 27905908, 2016). "In contrast, IL-6 levels did not significantly differ between severe and non-severe pneumonia in either serum or saliva (p > 0.47), indicating that IL-6 elevation occurs in pneumonia but was not a distinguishing factor for progression to critical illness in this cohort." (PMID 41018059, 2025).
pneumonia (continued). "Furthermore, we do not know the impact of intraamniotic inflammation and/or infection on the values of IL6 in NA in the first week of life, nor the impact of healthcare-related pneumonia that can occur typically after 7-10 days of MV in extremely preterm infants." (PMID 40173116, 2025). "Thus, we tested the levels of IL-6, TNF-α, and IL-1β in culture supernatants from macrophages, serum and BALF, and the results showed that LAA reduced the levels of IL-6, TNF-α, and IL-1β in culture supernatants from S. aureus-induced macrophages and serum and BALF of pneumonia mice." (PMID 38803378, 2024). "Moreover, administration of inhibitors targeting Stat3/IL-6 signaling could significantly attenuate the AC-induced pneumonia of non-permissive host mouse, providing an effective candidate target for intervention of this severe parasitic pneumonia." (PMID 35617354, 2022). "Furthermore, a significant increase in IL-6 was detected in the sera of hamsters co-infected with SARS-CoV-2 and IAV at 7 and 10 days post-infection, suggesting that IL-6 may be involved in the increased severity of pneumonia." (PMID 34711897, 2021). "Furthermore, in the third day of antibiotics therapy, IL6:IL10 serum levels higher than 5.0 predict persistence of the symptoms and may help medical decision in adjusting the therapeutics for severe cases, and discharge mild pneumonia cases." (PMID 27905908, 2016). "Several cytokines (CHI3L1, IL-1Rα, IL-6, G-CSF, MCP-1, and MIP-1α) were elevated in severe pneumonia cases, regardless of disease etiology." (PMID 41488910, 2025). "High levels of IL-6 and IL-10 could be useful biomarkers to discriminate non-COVID-19 pneumonia from COVID-19 pneumonia, which is in line with other reports where the IL-6 and IL-10 ratio has been suggested as a useful biomarker to discriminate severe pneumonia cases at admission." (PMID 40508859, 2025). "In this study, from the general clinical analysis, the proportion of dysphagia, NIHSS score, IL-6 and HNL levels in the group with pneumonia were higher than those in the group without pulmonary infectionsignificantly." (PMID 38233767, 2024). "IL-6 and CXCL10 levels were higher in patients with pneumonia than in those without it, regardless of their vaccination status." (PMID 38694512, 2024). "The levels of IL-6, CXCL10, LD, and CRP were significantly higher in patients with pneumonia than in those without pneumonia, both in the vaccinated and the unvaccinated group." (PMID 38694512, 2024). "Children with COVID-19 pneumonia showed higher levels of serum interleukin-6 (IL-6), interleukin-10 (IL-10), and tumor necrosis factors-α (TNF-α) than children without pneumonia." (PMID 37735372, 2023). "Analysis of the general health and biochemical data according to pneumonia revealed a significant correlation with neutrophile, IL-6, CRP levels (p = 0.01, p < 0.001, p < 0.001), as was found negative between pneumonia and lymphocytes (p < 0.001)." (PMID 37608339, 2023). "The results showed that the expression levels of IL-6, IFN-γ, IFN-α1, IP10, IL-10, HMGB1, and the HMGB1/sRAGE ratio were comparable between patients with or without pneumonia." (PMID 35875560, 2022). "Moreover, administration of inhibitors targeting Stat3/IL-6 could attenuate AC-induced pneumonia in nonpermissive host mice, corroborating that Stat3/IL-6 signaling mediates the AC-induced pneumonia and providing an effective candidate target for intervention of parasitic pneumonia." (PMID 35617354, 2022). "We found that high levels of IL-6, IFN-γ, and IL-2 and low levels of IL-5, IL-25, IL-17A, and IL-22 were found in the severe pneumonia group compared to the nonsevere pneumonia group." (PMID 34692846, 2021). "On laboratory testing, children with pneumonia had higher leukocyte counts and C-reactive protein (CRP), D-dimer, interleukin-6 (Il-6) and alanine as well as aspartate aminotransferase (ALT and AST) levels than patients without pneumonia." (PMID 34768620, 2021).
pneumonia (continued). "Relative to other non-macrolide antibiotics, azithromycin reduced levels of IL-6, IL-8, TNF-α and GM-CSF proteins in individuals with pneumonia and rhinovirus infections." (PMID 31306419, 2019). "Another study reported hyperactivation of IL-6, IL-8, and MCP-1 in blood of subjects infected with pandemic H1N1 that developed pneumonia and in complicated seasonal influenza, but not in milder pandemic H1N1 infections." (PMID 31275311, 2019). "Conversely, alveolar macrophages from patients with severe pneumonia displayed upregulated transcripts for IL-8, but not TNF and IL-6." (PMID 27413252, 2016). "Of the cytokines with predominantly pro-inflammatory effects investigated in our study, there were significantly higher concentrations of IL-1, IL-6 and TNF- in the plasma from children with severe pneumonia compared to the children with non-severe pneumonia." (PMID 26407163, 2015). "The levels of IL-6, CRP and WBCs, as well as mean body temperature were significantly higher in the patients with pneumonia than in the patients without pneumonia." (PMID 23935729, 2013). "The levels of IL-6, CRP and WBCs, and the mean body temperature were significantly higher in the pneumonia group than in the non-pneumonia group." (PMID 23935729, 2013). "Patients admitted with pneumonia and who presented with or developed concomitant S-AKI had higher plasma levels of IL-6 and TNF-α than did non-AKI patients." (PMID 22030145, 2011). "By comparing the hub genes with the top ten genes of pneumonia, we found 5 overlapping genes (IL-1B, IL-6, CXCL8, TNF, and IL-10), which might interpret on how the YPFG exerts a therapeutic effect in some types of pneumonia but not all types of pneumonia." (PMID 36285159, 2022). "Interestingly, decreased CASC2 levels showed a negative correlation with the levels of CRP, IL‐6, PCT, and D‐dimer in children with severe pneumonia." (PMID 35665444, 2022).